UBP1 (upstream binding protein 1)
Description:
Functions as a transcriptional activator in a promoter context-dependent manner. Modulates the placental expression of CYP11A1. Involved in regulation of the alpha-globin gene in erythroid cells. Activation of the alpha-globin promoter in erythroid cells is via synergistic interaction with TFCP2 (By similarity). Involved in regulation of the alpha-globin gene in erythroid cells. Binds strongly to sequences around the HIV-1 initiation site and weakly over the TATA-box. Represses HIV-1 transcription by inhibiting the binding of TFIID to the TATA-box.
Synonyms: TFCP2L5; LBP-1a; LBP-1B; LBP1A; LBP1B
Tractability: PROTAC: ubiquitination databases record sites on it; its protein half-life has been measured.
Gene: Protein-coding gene on chromosome 3 (33,388,336 to 33,441,407, reverse strand). Ensembl gene ENSG00000153560.
Subcellular location: Nucleus
Subcellular location (Human Protein Atlas): Nucleoplasm
Gene Ontology:
Molecular function: DNA-binding transcription activator activity, RNA polymerase II-specific; protein binding; RNA polymerase II cis-regulatory region sequence-specific DNA binding; sequence-specific double-stranded DNA binding; DNA-binding transcription factor activity, RNA polymerase II-specific; DNA-binding transcription factor activity
Biological process: negative regulation of viral transcription; positive regulation of transcription by RNA polymerase II; regulation of transcription by RNA polymerase II
Cellular component: nucleoplasm; nucleus; chromatin
Genetic constraint (gnomAD): Loss-of-function variants: 20 observed, 59.1 expected, observed/expected ratio (o/e) 0.34, 90% interval 0.24 to 0.49. The upper end of that interval is the gene's LOEUF score, 0.49, which puts it in group 2 of 6, group 1 being the genes least tolerant of losing a copy. Missense variants: 400 observed, 611.18 expected, observed/expected ratio (o/e) 0.65, 90% interval 0.6 to 0.71. Synonymous variants: 211 observed, 223.41 expected, observed/expected ratio (o/e) 0.94, 90% interval 0.84 to 1.06.
Homologues: Orthologues: chimpanzee UBP1 (99% identical), macaque UBP1 (99% identical), mouse Ubp1 (94% identical), rat Ubp1 (94% identical), pig UBP1 (93% identical), rabbit UBP1 (93% identical), guinea pig UBP1 (91% identical), dog UBP1 (89% identical), zebrafish ubp1 (71% identical), Drosophila melanogaster gem (39% identical), Caenorhabditis elegans grh-1 (18% identical). Paralogues in human: TFCP2 (68% identical), TFCP2L1 (59% identical), GRHL3 (24% identical), GRHL1 (23% identical), GRHL2 (23% identical).
Diseases named in the same sentence as UBP1 in open-access papers:
UBP1 is named in the same sentence as 16 diseases in open-access papers, as found by Europe PMC text mining. Sharing a sentence is not in itself a finding about the gene and the disease. The quoted sentences say what the papers report.
malaria (4 papers, 2007 to 2024). Malaria is a serious and sometimes fatal disease caused by a parasite that commonly infects a certain type of mosquito which feeds on humans. "AP-2μ and UBP1 mutations were detected in malaria patients imported from Africa and Southeast Asia to Wuhan, China." (PMID 39330912, 2024). "We acknowledge that we have yet to provide direct evidence of a role for mutations in UBP-1 in artemisinin resistance in the rodent malaria parasite P. chabaudi." (PMID 17581118, 2007). "However, two mutations in a ubiquitin hydrolase, UBP-1, have been previously associated with reduced artemisinin susceptibility in a rodent model of malaria, and some cases of UBP-1 mutation variants associated with artemisinin treatment failure have been reported in Africa and SEA." (PMID 32340987, 2020). "Furthermore, new resistance-related genes, in addition to the verified K13, AP-2μ, UBP1, and coronin, require validation and exploration to guide malaria control and drug development." (PMID 39330912, 2024). "However, whether the UBP1 IP → NT substitutions can change MDR1 protein trafficking in human malaria parasites need to be determined in future studies." (PMID 38413566, 2024). "This study reveals a previously unknown drug-resistant mechanism mediated by UBP1 through altered MDR1 localization and substrate transport direction in a mouse model, providing a new malaria treatment strategy." (PMID 38413566, 2024).
melanoma (2 papers, 2021 to 2023). A malignant, usually aggressive tumor composed of atypical, neoplastic melanocytes. "The mechanism for these changes in gene expression is in part due to induction of Tfcp2l1, a member of the TFCP2/TFCP2L1/UBP1 transcription factor subfamily that can serve as a pro-oncogenic factor in some tumors or in the case of melanoma, a tumor suppressor." (PMID 37270599, 2023). "Investigating negative-regulated target genes, we found eight genes (ANKRD13C, ARL5A, ATL3, PAWR, PDCD6IP, SLC16A7, TFAM, UBP1) presenting a significant inverse correlation with miR-181a/b expression also in melanoma A375 sensitive cells." (PMID 33670365, 2021).
breast carcinoma (1 paper, 2021). "The TFCP2/TFCP2L1/UBP1 TF subfamily is involved in various aspects of cancer development, including roles as pro-oncogenic factors in hepatocellular carcinoma as well as pancreatic and breast cancer." (PMID 33892791, 2021).
Hypertension (1 paper, 2009). The presence of chronic increased pressure in the systemic arterial system. "Approaches aimed at modulation of UBP1 activity and targeting the UBP1 driven genes could represent novel therapeutic approaches to treat hypertension and eventually other cardiovascular diseases." (PMID 19662162, 2009).
parasitemia (1 paper, 2020). "Mice were infected with a fixed inoculum of K13 and UBP-1 mutant parasites in four cohorts, and parasitemias were allowed to rise to ∼10%." (PMID 33173001, 2020).
cancer (5 papers, 2018 to 2025). A tumor composed of atypical neoplastic, often pleomorphic cells that invade other tissues. "The downregulation of RFX1 has been shown to predict poor prognosis in patients with small hepatocellular carcinoma, while TFCP2/TFCP2L1/UBP1 has been found to act as a TF in cancer." (PMID 32391054, 2020). "Furthermore, the association of TFCP2 and UBP1 with several cancer types, coupled with the parallels between certain mechanisms of placental development and tumor growth, have led to the recent study of TFCP2L1 as a prognostic marker for cancer." (PMID 40813991, 2025). "For example, there are numerous parallels between placental development and cancer growth; therefore, investigating the roles of TFCP2, TFCP2L1, and UBP1 in the placenta may help us better understand their functioning in cancer, as is evidenced by the studies of various other proteins and pathways." (PMID 30241344, 2018).
infection (3 papers, 2009 to 2017). The state of being infected such as from the introduction of a foreign agent such as serum, vaccine, antigenic substance or organism. "Although these granules do not represent canonical SGs, UBP1 is important for the formation of PVA-induced granules and seems to be one of the many host factors PVA employs to ensure a successful infection." (PMID 29312371, 2017).
UBP1 also shares sentences with these, for which no sentence is quoted: tumor (4 papers); atherosclerosis (1); cardiovascular diseases (1); Cerebral ischemia (1); cystic kidneys (1); endotoxemia (1); hepatocellular carcinoma (1); ovarian carcinoma (1); vascular tumor (1).